DKK1 (dickkopf Wnt signaling pathway inhibitor 1)
Diseases named in the same sentence as DKK1 in open-access papers (continued):
Sharing a sentence is not in itself a finding about the gene and the disease.
diabetes (30 papers, 2011 to 2026). "In patients with type 1 diabetes mellitus, high serum DKK1 and SOST were closely associated with both glycemic control and biochemical markers of bone turnover." (PMID 31197079, 2019). "Similarly, increased Dkk1 expression has been associated with the apoptosis of bone cells in femoral head osteonecrosis, with a low bone mineral density in children and adolescents with type 1 diabetes mellitus." (PMID 33287247, 2020). "Circulating DKK1 levels are higher in patients with diabetes and obese patients with insulin resistance compared with healthy controls." (PMID 40149867, 2025). "To elucidate the link between DKK1 and metabolic perturbations, we scrutinized DKK1 expression profiles in murine models of obesity, diabetes and PCOS, as well as in human subjects diagnosed with NAFLD." (PMID 41320970, 2025). "Recent findings have reported elevated DKK1 levels in individuals with obesity and those with type 2 diabetes mellitus (T2DM), displaying a positive correlation with body mass index (BMI)." (PMID 41320970, 2025). "In diabetic nephropathy models, knocking down DKK1 prevented diabetes-induced renal dysfunction and microstructure deterioration." (PMID 37942584, 2023). "Circulating DKK1 levels are high in type 2 diabetes mellitus, and a close relationship of DKK1 with cardiovascular disease has been revealed." (PMID 35355709, 2022). "Previous reports have demonstrated that the loss of DKK-1, a β-catenin inhibitor, leads to the repression of TGF-β1 and fibronectin in diabetes-induced renal fibrosis." (PMID 35565995, 2022). "Plasma DKK-1 levels were lower in heathy controls than in patients with diabetes, with increased platelet activity reflected by high urinary 11-dehydro-thromboxane B2, and aspirin was found to reduce plasma DKK-1 levels in patients with diabetes." (PMID 36291617, 2022). "DKK-1 expression was significantly elevated in KLF10 knockout diabetes group compared with KLF10 knockout alone (p < 0.05)." (PMID 35565995, 2022). "Downregulation of KLF10 diminished the expression of DKK-1 and phosphorylated β-catenin in the diabetes group." (PMID 35565995, 2022). "Elevated DKK-1 and phosphorylated β-catenin were observed in the diabetes group compared with the control alone." (PMID 35565995, 2022). "This study aims to investigate the effects of KLF10 on renal fibrosis-related proteins including TGF-β1 and DKK1 pathway expression in STZ-induced diabetes by using KLF10 knockout mice." (PMID 35565995, 2022). "The expression of diabetes-induced DKK-1 and phosphorylated β-catenin was mitigated in the KLF10 knockout group." (PMID 35565995, 2022). "In this study, we extend these findings to further demonstrate the role of GSK-J4 in regulating diabetes-induced glomerulosclerosis via DKK1." (PMID 36012674, 2022). "The long-term effects of plasma DKK-1 on the population with diabetes should be further investigated." (PMID 36291617, 2022). "The expression levels of DKK-1 and phosphorylated β-catenin were obviously elevated in the diabetes group compared with the normal control group." (PMID 35565995, 2022). "High-power field microscopic analysis of glomerular mesangium further demonstrated that miR-29a transgenic mice expressed higher β-catenin and lower DKK1 than wild-type mice after induction of diabetes." (PMID 27460630, 2016). "Consistent with this notion, our data also showed that gain or loss of miR-29a function proportionally altered the expression of DKK1 and β-catenin in both in vitro and in vivo models of diabetes." (PMID 27460630, 2016). "Currently, very little is known about the upstream regulation of DKK1 and Wnt/β-catenin signaling in diabetes-induced renal fibrosis." (PMID 27460630, 2016). "Since sclerostin and DKK1 levels are significantly elevated in diabetes and Wnt pathways also participate in glucose metabolism and T2DM development, recent studies have begun to focus on whether these antibodies also exert an effect on glucose homeostasis." (PMID 40149867, 2025).
diabetes (continued). "The result is reduced osteoblast activation and increased osteoclastogenic factors, which are responsible for reduced bone turnover in individuals with diabetes, implicating that hyperglycemia can have a direct negative effect on bone metabolism in young patients by increasing DKK-1 levels." (PMID 37106471, 2023). "DKK1 effectively decreased diabetes-induced glomerular fibrosis." (PMID 36012674, 2022). "Diabetes significantly impaired bone defect healing in both Dkk1-deficient and wildtype mice, suggesting that Dkk1 does not play a prominent role in bone defect healing." (PMID 33479403, 2021). "Our results are in line with those of other authors that report a negative association between circulating Dkk-1 and arterial calcified plaques in type 2 diabetes mellitus." (PMID 33574979, 2021). "Finally, we assessed the impact of Dkk1 knockout in late osteoblasts/osteocytes on bone defect healing, as fracture healing is frequently impaired in patients with diabetes." (PMID 33479403, 2021). "In the study, we investigated whether miR-29a signaling participates in mesangial fibrosis induced by hyperglycemia, and elucidated the relationship between miR-29a action and the DKK1/Wnt/β-catenin signaling in diabetes-induced renal injury." (PMID 27460630, 2016). "Considering that inhibition of WNT signaling improves function of PDLSCs, as we reported in this study, DKK1 or a small molecule that mimic its function may help PDLSCs server as a potential agent to treat periodontitis patients with diabetes mellitus." (PMID 26278788, 2015). "Our results indicate that DKK-1 may mediate KFL10-induced fibrogenesis in diabetes conditions." (PMID 35565995, 2022). "This study aimed to investigate the correlation between sclerostin and DKK1 levels and PAS in patients with type 2 diabetes mellitus (T2DM)." (PMID 42075515, 2026). "On the other hand, mRNA expressions of DKK1, BMP-2, OSN, RUNX2, and LRP5, which decrease with diabetes in bone tissue, increase significantly with MF administration." (PMID 39202505, 2024). "For other Wnt/β-catenin signalling molecules, the levels of Wnt signalling inhibitors (sclerostin and DKK1) were increased, whereas the levels of Wnt ligands (Wnt3a and Wnt10) were unaltered in STZ-induced diabetes rats." (PMID 37569816, 2023). "Lin and colleagues showed that reduced expression of the endogenous inhibitor, DKK-1, which binds Wnt co-receptors LRP5/6, decreased diabetes-induced glomerular injury preventing hyperglycaemia-induced mesangial cell dysfunction." (PMID 21876774, 2011). "Previous studies have revealed a negative association between circulating DKK1 and arterial stiffness in CKD patients and calcified plaques in cases of type 2 diabetes mellitus." (PMID 31477034, 2019). "There are no previous studies evaluating differences in serum DKK1 concentrations according to the presence of diabetes." (PMID 25369286, 2014). "The changes seen for DKK1, cathepsin A, cathepsin S, cathepsin Z, and FGF23 that potentially favor a bone resorptive state may contribute to the resorptive effects of RANKL in diabetes." (PMID 41373586, 2025).
glioma (30 papers, 2010 to 2025). A benign or malignant brain and spinal cord tumor that arises from glial cells (astrocytes, oligodendrocytes, ependymal cells). "According to the GEPIA database, for patients with glioma, higher DKK1 expression is associated with shorter survival time." (PMID 37906341, 2023). "The aim of this study was to examine the expression profile of DKK-1 gene in human glioma and its association with tumor malignancy." (PMID 21029453, 2010). "Because DKK-1 encodes a secreted protein, we investigated the DKK-1 protein secreted into sera of patients with glioma or neuronal benign tumor and healthy individuals." (PMID 21029453, 2010). "Furthermore, studies have revealed that elevated levels of DKK1 are linked to the poor prognosis of gliomas." (PMID 37906341, 2023). "As previously reported, DKK1 is upregulated in glioma cells and tissues, which is similar to the results of this study." (PMID 37906341, 2023). "Interactions among UBA2, RALY, FOXD1, and DKK1 play an important role in regulating migration, invasion, and vasculogenic mimicry in glioma cells." (PMID 37906341, 2023). "Silencing of FOXD1 downregulated the expression of DKK1 by inhibiting its transcription and, thus, decreased migration, invasion, and vasculogenic mimicry in glioma cells." (PMID 37906341, 2023). "Knockdown of DKK1 significantly reduced cell proliferation by inhibiting the PI3K-AKT pathway in glioma." (PMID 37906341, 2023). "Subsequently, we explored the effects of DKK1 knockdown and found that it attenuated the vasculogenic networks in glioma cells and decreased the expression levels of metalloproteinases MMP2 and MMP9 and VE-Cadherin." (PMID 37906341, 2023). "The overexpression of FOXD1 promotes DKK1 transcription by activating its promoter, thereby promoting glioma cell migration, invasion, and VM." (PMID 37906341, 2023). "In this study, we found that the expression levels of UBA2, RALY, FOXD1, and DKK1 were significantly increased in glioma cells and tissues and were negatively correlated with the overall survival time in glioma patients." (PMID 37906341, 2023). "It has been recognized by some studies that Dkk1 can be overexpressed in several different cancer cell lines, including liver, lung, breast, glioma, and cervical cancer, and it inhibits cell proliferation and differentiation by inducing apoptosis." (PMID 36139498, 2022). "A previous study revealed that the induction of DKK1 expression by hypoxic stimulation contributes to the intense adaptation of glial tumor cells to environmental alterations." (PMID 33420361, 2021). "One study showed that DKK1 expression led to glioma cell sensitivity to chemotherapy-induced apoptosis." (PMID 31073965, 2019). "CBX7 overexpression decreases Wnt/β-catenin signaling and blocks glioma cell invasion mediated by DKK1, which was verified in LN229, T98G and PGC cell lines." (PMID 28388562, 2017). "In contrast to DACH1, epigenetic changes were reported to play a role in reducing DKK1 expression in gliomas." (PMID 26337424, 2016). "In head and neck cancer cells, decreased DKK1 expression was associated with acquired cisplatin resistance, whereas overexpression of DKK1 in a glioma cell line sensitized these cells to DNA damaging agents including cisplatin." (PMID 26353782, 2015). "Conversely, one study showed that DKK1 enhances glioma-tumor angiogenesis by negatively regulating delta-like ligand-4." (PMID 24091497, 2014). "We screened 58 tissue samples embedded in paraffin blocks by immunohistochemistry and identified expression of DKK-1 protein located at cytoplasm (with granular appearance) of the great majority of the glioma samples examined." (PMID 21029453, 2010). "Expression of DKK-1 mRNA and protein was undetectable in medulloblastoma cells, low-grade glioma cells, and human astrocytes." (PMID 21029453, 2010). "Although secreted Wnt antagonists have been found to be down-regulated or silenced in certain carcinomas, DKK-1 expression is restored in glioma cells." (PMID 21029453, 2010).
glioma (continued). "In the current study, we analyzed the expression of DKK-1, an antagonist of Wnt signaling, in clinical glioma materials and cell lines at the mRNA and protein level." (PMID 21029453, 2010). "To identify the association of DKK-1 expression with pathologic tumor classification, we did DKK-1 expression profile analysis in patients at various clinical stages of glioma and in healthy controls." (PMID 21029453, 2010). "ELISA experiments detected DKK-1 protein in serologic samples from 18 patients with spongbioblastoma or low-grade glioma, 20 benign tumor patients in their neuronal system, and 8 healthy controls." (PMID 21029453, 2010). "We determined the expression levels of DKK-1 transcript and protein in 12 glioblastoma cell lines, medulloblastoma cells, low-grade glioma cells, and human astrocyte cells by semiquantitative RT-PCR and ELISA." (PMID 21029453, 2010). "We first sought to identify the differential expression of the DKK-1 gene in 12 glioblastoma cell lines, medulloblastoma cells, low-grade glioma cells, and human astrocytes as a control using semi-quantitative RT-PCR analysis." (PMID 21029453, 2010). "Our findings are confirmed by immunohistochemical stainings of DKK-1 in glioma and normal human brain tissue." (PMID 21029453, 2010). "FOXD1 stabilization promotes vasculogenic mimicry in glioma cells by activating DKK1 transcription." (PMID 40999468, 2025). "In this study, it showed the highly expression of DKK1 in glioma." (PMID 37906341, 2023). "Here, we investigated the functional role of DKK1 on glioma cells." (PMID 37906341, 2023). "The results confirmed that FOXD1 transcriptionally activated DKK1 expression in glioma cells." (PMID 37906341, 2023). "Human umbilical cord‐derived MSCs inhibit C6 glioma cell growth by secreting DKK1." (PMID 37410396, 2023). "In addition, we profiled the expression of UBA2, RALY, FOXD1, and DKK1 and explored the probable interaction mechanism among these molecules in the regulation of vasculogenic mimicry (VM) in glioma." (PMID 37906341, 2023). "It was observed that the DKK1 expression was significantly elevated in glioma." (PMID 37906341, 2023). "UBA2/RALY/FOXD1/DKK1 axis may play crucial roles in regulating VM in glioma, which may contribute to the development of potential strategies for the treatment of gliomas." (PMID 37906341, 2023). "The AD-MSCs could inhibit lymphoblast proliferation, and UC-MSCs inhibited the growth of C6 glioma cells; both act through the DKK1-Wnt/β-catenin signaling pathway." (PMID 37287079, 2023). "Additionally, in an in vivo study, the overexpression of DKK1 in mouse glioma cells promotes tumor growth, angiogenesis, and subcutaneous xenograft tumor formation in nude mice." (PMID 37906341, 2023). "In addition, we found that the inhibition of UBA2, RALY, FOXD1, and DKK1 inhibited glioma cell migration, invasion, and vasculogenic mimicry." (PMID 37906341, 2023). "This is consistent with a carcinogenic function for DKK1 in glioma." (PMID 36418306, 2022). "The expression of DKK1 in GBM was significantly higher than that in LGG, and survival analysis showed that low expression of DKK1 was associated with a better prognosis in gliomas." (PMID 36418306, 2022). "We subsequently investigated whether DKK1 is a negative regulator of Wnt signaling in glioma cells overexpressing CBX7." (PMID 28388562, 2017). "We also show that DACH1 and DKK1 methylation is an infrequent event in glioma." (PMID 26337424, 2016). "In the present study, we observed that DKK-1 transcript and protein widely express in glioma cell lines and pathologic tumor tissues with increased levels but not in medulloblastoma cell line D341, indicating different expression pattern of DKK-1 in intracranial neuroepithelial carcinomas." (PMID 21029453, 2010). "Our results indicated that DKK-1 has a pro-apoptotic function of in glioma." (PMID 20920327, 2010). "The aim of this study is to further examine the function of DKK-1 in glioma cells." (PMID 20920327, 2010).
glioma (continued). "Elevated DKK-1 levels are also found in cerebrospinal fluid of glioma patients." (PMID 21029453, 2010). "Thus, DKK-1 can serve as a marker for diagnosis of glioma through detecting the expression of the protein and mRNA of DKK-1." (PMID 21029453, 2010). "The Wnt antagonist DKK-1 gene may have important roles in glioma tumorigenesis and act as a novel biomarker in human malignant glioblastoma." (PMID 21029453, 2010). "In this paper we report that the role of DKK-1, an inhibitor of the Wnt pathway, in gliomas." (PMID 21029453, 2010). "It remains unclear if the increased DKK-1 expression is in response to Wnt activation in gliomas or independent effect." (PMID 21029453, 2010). "Our data suggest the possible roles of DKK-1- in carcinogenesis of gliomas." (PMID 21029453, 2010). "The proportion of the DKK-1-positive cases was 91.5% for glioma (43 of 47)." (PMID 21029453, 2010). "The high level of DKK-1 protein in most glioma cell lines suggested that DKK-1 may play an important role in glioma and attracted our intention to further study this DKK-1's function in glioma." (PMID 20920327, 2010). "Moreover, DKK1 knockdown inhibited glioma cell migration, invasion, and VM." (PMID 37906341, 2023). "However, an in-depth mechanism of the functional role of FOXD1 and DKK1 in glioma VM remains unknown." (PMID 37906341, 2023). "The inhibitor of UBA2, RALY, FOXD1, and DKK1 may serve as the therapeutic target in glioma." (PMID 37906341, 2023). "Similarly, there are also reports about a DKK1 pro-apoptotic function in glioma." (PMID 34064046, 2021). "However, little is known about the control mechanism of DKK-1 expression in human gliomas." (PMID 21029453, 2010). "Overexpression of DKK1 rescued the suppression of migration, invasion, and VM induced by FOXD1 knockdown in glioma cells." (PMID 37906341, 2023). "However, the effect of DKK1 on migration, invasion, and VM in glioma cells remains unclear." (PMID 37906341, 2023). "In this study, the differential expression of DKK1 was evaluated in both low-grade gliomas (LGG n = 530) and high-grade gliomas (GBM n = 166) using The Cancer Genome Atlas (TCGA) dataset." (PMID 36418306, 2022). "Based on our data, CBX7 should be added to this growing list of β-catenin regulators in glioma that includes SFRP1, DKK1 and Wif1." (PMID 28388562, 2017). "Beside the genes, which were described earlier as possible targets of epigenetic silencing in gliomas (SFRP1, SFRP2, DKK1), the methylation of PPP2R2B, SOX17, and DACH1 was also assessed." (PMID 26337424, 2016). "Dysregulation of the Wnt canonical pathway leading to beta-catenin activation has been detected in glioma patients with overexpression of WNT3a and epigenetic-driven downregulation of inhibitors like SFRP1, Dkk1 or Wif1." (PMID 27613837, 2016). "The methylation of SFRP1, SFRP2, PPP2R2B, DKK1, SOX17, and DACH1 was analyzed in 64 glioma samples using methylation-specific polymerase chain reaction (MSP)." (PMID 26337424, 2016). "ASCL1 removes the negative regulation of Wnt, normally imposed by Dickkopf Wnt signaling pathway inhibitor 1 (DKK1), a process that was shown to be necessary for glioma CSC tumorigenicity." (PMID 27043632, 2016). "DKK1 is a target gene of the Wnt pathway, and PRDM1 has recently been proposed to enhance DKK1 levels through an alternative mechanism in glioma cells." (PMID 24733089, 2014). "Thus, we conclude that DKK-1 may have an important role in glioma tumorigenesis." (PMID 21029453, 2010). "It has been reported that DKK1 is a direct target of Wnt signaling in various cells and that FOXM1 binds directly to β-catenin and promotes its nuclear localization and β-catenin-dependent transcriptional activity in glioma cells." (PMID 34117362, 2021). "The discrepancy between glioma tumor results and our B16F10 tumor data may be explained by the complexity of Wnt signaling components and different DKK1 delivery methods." (PMID 24091497, 2014).
glioma (continued). "Recently, we found that 9 out of 12 human glioma cell lines had high level of DKK-1 protein while the other 3 had very low or non-detectable level of DKK-1." (PMID 20920327, 2010). "In this study we constructed a eukaryotic expression vector of human DKK-1(pcDNA3.1-DKK-1) and stably transfected the vector into the glioma cell line SHG44, which had no expression of DKK-1 under normal growth condition." (PMID 20920327, 2010). "However, there are few studies investigating the expression of DKK1 and DKK3 in gliomas." (PMID 34064046, 2021).